TNF (tumor necrosis factor)
Diseases named in the same sentence as TNF in open-access papers (continued):
Sharing a sentence is not in itself a finding about the gene and the disease.
pneumonia (continued). "High levels of TNF-α can damage capillary endothelial cells, promote microthrombosis, and lead to ischemic necrosis; thus, TNF-α is related to the severity of pneumonia." (PMID 33134293, 2020). "After adjusting for age, NIHSS score, pneumonia, WBC count, plasma IL-6, and TNFα release, the OR for poor functional outcome was 2.32 (95% CI 1.21–4.45, P = 0.01)." (PMID 32107751, 2020). "The 6 studies, respectively, showed that the TNF-α level of the XBJ group was lower compared with the control group with statistical significance indicating that XBJ combined with basic treatment could reduce the level of TNF-α in patients with severe pneumonia." (PMID 32908573, 2020). "The levels of the pro-inflammatory cytokines/chemokines including TNF-α, IL-1β, IL-6, MCP-1 and KC were significantly higher in the HNP+ pneumonia mice under HP ventilation than other groups." (PMID 30268129, 2018). "Patients with a history of ILD and exposure to tocilizumab or rituximab were more likely to have a baseline history of pneumonia (25.4 % and 24.2 % versus 15.1 %) and COPD (22.0 % and 27.3 % versus 17.7 %) compared with patients exposed to anti-TNF therapy." (PMID 26555431, 2015). "Therefore, TNF-α may play a pivotal role in the development of pneumonia." (PMID 23577187, 2013). "Moreover, TNF-α −308A/G polymorphism did not play a role in the pneumonia mortality risk." (PMID 23577187, 2013). "It was therefore unexpected that PAR-1 KO mice displayed higher concentrations of the proinflammatory cytokines TNF-α, IL-6 and IFN-γ in lung tissue during pneumonia." (PMID 23270594, 2012). "In fact, these viruses markedly induced the expressions of pro-inflammatory cytokines and chemokines including IL6, IL1α, IL1β, TNFα, IFNγ and CCL5 in the lungs, resulting in severe pneumonia." (PMID 21826229, 2011). "After hemorrhage, a preventive treatment with CpG-ODN or Monophosphoryl Lipid A increased transcriptional activity in DCs (TNF-α, IFN-β and IL-12p40) and decreased mortality of post-hemorrhage MSSA pneumonia." (PMID 20949109, 2010). "In our CF mice with PA508 pneumonia, E2 increased protein levels in BAL fluid of TNFα and IL-6 (upstream stimulators of IL-17 production) and also increased mRNA levels in lung tissue of IL-23 and the isoforms IL-17A and IL-17F." (PMID 21118573, 2010). "Additionally, intestinal gram-negative bacterial overgrowth secondary to vancomycin treatment, although associated with slightly higher plasma TNF-α and IL-10 concentrations shortly after induction of pneumonia, did neither influence host defense or lung pathology during P. aeruginosa pneumonia." (PMID 19710930, 2009). "Besides, another study also explored the immune reactions in Chlamydia psittaci pneumonia and they found psittacosis cases with pneumonia had higher levels of serum cytokines (G-CSF, IL-2, IL-6, IL-10, IL-18, IP-10, MCP-3, and TNF-α) than bronchitis cases." (PMID 40236451, 2025). "In a murine pneumonia model, a high-CBD extract significantly reduced neutrophil migration to the lungs and lowered pro-inflammatory cytokines like IL-1β, MCP-1, IL-6, and TNF-α." (PMID 40599866, 2025). "In addition, IL-2, IL-4, IL-6, IL-10, TNF-α, and IFN-γ levels were elevated by varying amounts depending on the type of pneumonia." (PMID 41011430, 2025). "Some studies have reported that radiotherapy could prompt alveolar epithelial cells to release many cytokines, such as TNF-α, IL-6, IL-13, and TGF-β1, which in turn affect the development of pneumonia." (PMID 40821765, 2025). "Additionally, the levels of the inflammatory cytokines IL-1β, IL-6, and TNF-α in bronchoalveolar lavage fluid (BALF) and plasma were significantly elevated in mice receiving FMT from patients with pneumonia." (PMID 40736248, 2025).
pneumonia (continued). "After conducting LD analyses and eliminating confounding variables, the ultimate counts of IVs for CRP, SAA1, IL-6, TNF-α, WBC, GlycA, GI, dysentery, pneumonia, BP, BLA, PP, and UTI are 1,594, 1,959, 1,021, 1,911, 1,597, 1,871, 1,870, 1,965, 1,876, 1,875, 1,864, 1,877, and 1,888, respectively." (PMID 38585702, 2024). "After immunotherapy, the proportion of circulating NK cells and the level of TNF-α increased, and the cell densities of PD-1+ cytotoxic T cells decreased in patients without pneumonia." (PMID 38343550, 2024). "The key findings were as follows: the serum levels of IL-4, TNF-α, IL-17A, and IL-12p70 were higher than those in the pneumonia without headache group, and the serum level of IL-12p70 was higher than that in the encephalitis with headache group." (PMID 38356891, 2024). "Children with COVID-19 pneumonia showed higher levels of serum interleukin-6 (IL-6), interleukin-10 (IL-10), and tumor necrosis factors-α (TNF-α) than children without pneumonia." (PMID 37735372, 2023). "Meanwhile, the results of molecular docking also exposed the active ingredients of YPFG could tack a part in modulating the progression of pneumonia via MMP9, CCL2, IL-1B, IL-6, CXCL8, and TNF." (PMID 36285159, 2022). "By comparing the hub genes with the top ten genes of pneumonia, we found 5 overlapping genes (IL-1B, IL-6, CXCL8, TNF, and IL-10), which might interpret on how the YPFG exerts a therapeutic effect in some types of pneumonia but not all types of pneumonia." (PMID 36285159, 2022). "Elevated concentrations of both pro- and anti-inflammatory plasma cytokines were observed in the pneumonia group, including G-CSF, HGF, IL-1b, IL-1RA, IL-2, IL-2Ra, IL-6, IL-10, IL-18, IP-10, monocyte chemoattractant protein-3 (MCP-3), and TNF-α." (PMID 36119044, 2022). "TNF‐α specifically reflects lung injury severity rather than diagnosis as it is higher in patients with ARDS even compared to those with severe pneumonia, as reported by Bauer (2000)." (PMID 34250766, 2021). "Existing evidence suggests a relationship between the intensity of the inflammatory response indicated by measured blood levels of inflammatory marker such as interleukin (IL)-6, IL-8, IL-10, tumor necrosis factor (TNF)-α in the blood and the severity of pneumonia and subsequent mortality." (PMID 34071031, 2021). "After LPS stimulation, alveolar (p = 0.027) and blood (p = 0.005) monocytes from pneumonia-related ARDS patients had a significantly lower intracellular TNF expression than non-ARDS patients." (PMID 34944055, 2021). "The primary aim of this study was to evaluate alveolar monocyte functions in patients with severe pneumonia and ARDS by exploring their phagocytosis capacity and intracellular TNF production after LPS exposure, together with their relationship with HLA-DR expression." (PMID 34944055, 2021). "We thus assessed the intracellular TNF production of both circulating and alveolar monocytes obtained from pneumonia-related ARDS patients and non-ARDS patients." (PMID 34944055, 2021). "Significantly higher plasma levels of IL-2, IL-7, IL-10, G-CSF, IP-10, MCP-1, MIP-1α, and TNFα were found in patients with severe pneumonia developing ARDS compared to non-ICU patients showing pneumonia without ADRS." (PMID 34578468, 2021). "Among 89 elderly patients with severe pneumonia, the SFI treatment group had significantly decreased levels of TNF-α, IL-6, and IL-8 7 days after administration, indicating that SFI effectively reduced inflammatory mediators, thus, playing an active therapeutic effect." (PMID 32848729, 2020). "Although TNFα levels were also higher in patients who developed DHF compared to those who developed severe pneumonia, this was not significant (p = 0.29)." (PMID 33199778, 2020). "Low TNF-α producers had a higher PSI indicating that patients who are most immune suppressed have more severe pneumonia; however, this was not reflected by longer hospital stays or significantly higher mortality rates." (PMID 32477337, 2020).
pneumonia (continued). "In addition, significant increase was observed in the TNF-α, IL-6, IL-1β, and MPO in the BALF and lung tissue samples collected from the KP-infected pneumonia mice, which were reversed by anemoside B4." (PMID 32625244, 2020). "The values of sTREM-1 and TNF-α were higher in the experimental group than in the control group, but they did not increase with the severity of pneumonia." (PMID 31387541, 2019). "The levels of IL-6, TNF-α, and C-reactive protein were positively correlated with the serum levels of YKL-40, but the IL-10 levels were negatively correlated with YKL-40 levels in all 3 pneumonia subgroups." (PMID 30514252, 2018). "Pneumonia resulted in increased pulmonary concentrations and gene expression of both IL-8 and IL-1β, but not TNF-α." (PMID 30082877, 2018). "In the present study, the cytokines, TNF, IL-1β, IL-6, IL-8, IL-12p70, IFN-γ, IL-17A, IL-10 and IL-5, were detected in the serum of children with pneumonia and severe pneumonia at hospital admission, and IL-6 was the only cytokine associated with disease severity." (PMID 27905908, 2016). "Conversely, alveolar macrophages from patients with severe pneumonia displayed upregulated transcripts for IL-8, but not TNF and IL-6." (PMID 27413252, 2016). "Of the cytokines with predominantly pro-inflammatory effects investigated in our study, there were significantly higher concentrations of IL-1, IL-6 and TNF- in the plasma from children with severe pneumonia compared to the children with non-severe pneumonia." (PMID 26407163, 2015). "One male patient under anti-TNFα + CS therapy died from pneumonia of presumed viral etiology, whereas no other mortality or permanent sequelae were observed as a consequence of infections." (PMID 24655394, 2014). "In comparison with the sham control group, gonadectomized male mice showed significant decrease of bacilli loads and pneumonia, as well as higher expression of TNF-α (p = 0,001), IL-12 (p = 0,004) and IFN-γ (non-significant)." (PMID 24722144, 2014). "TNF-α is produced during the early phase of pneumonia, and its short half life probably explains the absence of detectable levels at 48 hours." (PMID 15707485, 2005). "Importantly, blocking TNFα, one of the SASP factors, altered the senescent-like phenotype and boosted the antibacterial activity of PMNs from aged hosts and increased host resistance to S. pneumoniae pulmonary infection." (PMID 41771759, 2026). "Studies have shown that propionate mitigates pneumonia severity and lung tissue remodeling by reducing the infiltration of neutrophils, eosinophils, and lymphocytes, and by interfering with the release of chemokine C-X-C Motif Chemokine Ligand 1(CXCL1) and inflammatory factor TNF-α." (PMID 40647346, 2025). "In contrast, treatment with increasing concentrations of TNF-α significantly decreased benzamil-sensitive Isc in HBECs starting at concentrations of ≥ 0.05 ng/mL which was similar to plasma levels observed in patients with acute lung injury, severe COPD or pneumonia." (PMID 39052685, 2024). "TNF-α in migraine group [5.60 (4.23) pg/mL], in encephalitis with headache group [5.02 (5.03) pg/mL], and in pneumonia without headache group [2.66 (2.97) pg/mL] showed that there were significant differences in the overall distribution of TNF-α levels among the three groups (H = 28.08, p < 0.0001)." (PMID 38356891, 2024). "Thus, we tested the levels of IL-6, TNF-α, and IL-1β in culture supernatants from macrophages, serum and BALF, and the results showed that LAA reduced the levels of IL-6, TNF-α, and IL-1β in culture supernatants from S. aureus-induced macrophages and serum and BALF of pneumonia mice." (PMID 38803378, 2024). "Compared with encephalitis with headache symptoms group and pneumonia without headache symptoms group the serum levels of IL-4, TNF-α, IL-17A, and IL-12p70 were higher in migraine group than in pneumonia group, and the levels of IL-12p70 were higher than those in encephalitis group (p < 0.05)." (PMID 38356891, 2024).
pneumonia (continued). "Moreover, the elevation of TNF‐α, IL‐1β, and NLRP3 was more pronounced in KD than in children with pneumonia, which may be related to the storm of inflammatory factors triggered by immune imbalance in KD." (PMID 37773705, 2023). "Notably, pneumonia patients who develop acute kidney injury were older, had more comorbidities, and higher levels of inflammatory cytokines in the blood (IL-6, TNF, D-dimer) even in those without severe disease." (PMID 36870980, 2023). "Therefore, based on these findings, we speculate that the target proteins by the three hub components are involved in TNF signaling pathway, which plays possible regulation amid YHPGKL against pneumonia." (PMID 36389108, 2022). "IT administration of 106 CFU MDR‐PA induced nonlethal but a robust pneumonia‐induced acute lung injury over 24 h, characterized by an influx of white blood cells, neutrophils, high levels of TNF‐α and MIP‐2, increased lung protein permeability, and development of bacterial load in BALF." (PMID 33463070, 2021). "Measurement of inflammatory cytokine levels using ELISA showed that IL-1β, IL-6, TNF-α, IL-2, IL-8, IL-12, and IFN-γ levels were significantly enhanced, while IL-10 levels were significantly reduced in the lung homogenates of Spn-induced pneumonia mice, compared with the normal mice." (PMID 32460745, 2020). "Taken together, the increased expression of IFN-α, TNF-α, IL-8, and FasL mRNA in AMs from pigs in various infection orders by PCV2 and PRRSV observed in the present study, to some extent may contribute to pneumonia and bronchiolar epithelial damage in the lungs of PCV2- and/or PRRSV-infected pigs." (PMID 23009687, 2012). "Principal changes were a) increase of absolute monocyte counts; b) selective defect of TNFα and IFNγ production from PBMCs after stimulation with S.pneumoniae; and c) increase of absolute counts of Tregs mainly observed among patients with H1N1-related pneumonia." (PMID 20037642, 2009). "During pneumonia induced by either encapsulated or non-encapsulated Spneu, Stk11-ΔM and control mice had comparable bacterial loads and inflammatory responses in the lung, with the exception of lower TNFα levels in Stk11-ΔM mice after infection with the non-encapsulated strain." (PMID 36096803, 2022). "Interestingly, in pneumonia-induced ARDS, this liver-derived acute-phase response occurs independently of bacterial dissemination and depends instead on inflammatory signaling molecules derived from the pulmonary immune cells, such as the cytokines IL-1, IL-6, and TNF-α." (PMID 33336286, 2020). "A 30-year-old CD patient treated with the TNF-α inhibitor, adalimumab, was infected by SARS-CoV-2 but recovered shortly after mild pneumonia without recurrence of CD." (PMID 39538233, 2024). "In comparison with non-treated control mice, treated animals with IDO blocker showed a non-significant decrease of pulmonary bacillary counts and lesser expression of IFN-γ, IL-4, TNF-α, and TGF-β, as well as lesser pneumonia, but these were non-significant." (PMID 37284503, 2023). "As shown from the pneumonia samples, representative proinflammatory cytokines such as IL-6, IL-1β, IL-4, IFN-γ, and TNF-α were adsorbed to the DND irrespective of the disease type." (PMID 35445003, 2022). "Patients admitted with pneumonia and who presented with or developed concomitant S-AKI had higher plasma levels of IL-6 and TNF-α than did non-AKI patients." (PMID 22030145, 2011). "Significantly higher plasma levels of IL-2, IL-7, IL-10, G-CSF, IP-10, MCP-1, MIP-1α, and TNFα were found in patients with severe pneumonia developing ARDS and requiring ICU admission and oxygen therapy compared to non-ICU patients showing pneumonia without ADRS." (PMID 33362782, 2020).
pneumonia (continued). "However, regulatory T cells (Tregs), cytokines (TGF-β1 and TNF-α), and DAMPs (HMGB1) do not play a significant role in the induction of paralyzed AMs during resolution of pulmonary inflammation following pneumonia." (PMID 32849610, 2020). "In comparison with the control group, animals that received blocking HMGB1 antibodies after 60 days of infection showed a significant increase of pulmonary bacilli burdens, lower expression of IFNγ, TNFα and IL17, high expression of IL-10, and higher but not significant pneumonia (39+/3% vs 32+/3%)." (PMID 26201072, 2015).